GSDMD (gasdermin D)
Diseases named in the same sentence as GSDMD in open-access papers (continued):
Sharing a sentence is not in itself a finding about the gene and the disease.
Sepsis (continued). "In the context of sepsis, excessive formation of NETs is correlated with pulmonary dysfunction, and inhibition of the gasdermin D pathway has been demonstrated to attenuate NETs release and enhance clinical outcomes." (PMID 39972252, 2025). "Inhibition of caspase-1 suppresses NLRP1 inflammasome signaling, gasdermin D (GSDMD) cleavage, and the maturation of IL-1β and IL-18, thereby ameliorating sepsis-induced acute kidney injury." (PMID 41262247, 2025). "Studies on the pathophysiology of pyroptosis in sepsis have mainly focused on the GSDMD and NLRP3-mediated signaling pathways." (PMID 40458798, 2025). "For instance, in sepsis models, O-GlcNAc modification of GSDMD at Ser338 disrupts its interaction with caspase-11, attenuating pyroptosis in HUVECs." (PMID 41280891, 2025). "For instance, phillyrin prevented sepsis-induced acute lung injury through inhibiting the NLRP3/caspase-1/GSDMD-dependent pyroptosis signaling pathway." (PMID 40708650, 2025). "For instance, TPNs have been shown to alleviate sepsis-induced damage by inhibiting GSDMD oligomerization." (PMID 39994107, 2025). "To further explore the mechanism of GSDMD in hepatocytes in inhibiting inflammation response in sepsis, we performed serum proteomic analysis and found that anti‐inflammatory factors such as VEGF‐B and Gremlin‐1 were significantly reduced in GSDMDhep‐/− mice." (PMID 40856013, 2025). "Notable candidates include MCC950, a selective NLRP3 inhibitor; anti–IL-1β monoclonal antibodies; and emerging GSDMD inhibitors, all of which aim to suppress the hyperinflammatory milieu of sepsis." (PMID 40558557, 2025). "As pyroptosis emerges as a central mechanism in sepsis pathogenesis, GSDMD‐targeting therapies have entered clinical testing." (PMID 41284375, 2025). "Another novel GSDMD inhibitor, NU6300, interacts with Cys191, impairing palmitoylation of the full-length GSDMD and GSDMD-NT, suggesting its extensive effects in sepsis treatment." (PMID 40461967, 2025). "Transfer of GSDMD-expressing WT neutrophils into GSDMD−/− mice reversed the protective effect of the organs against sepsis and elevated serum NET levels." (PMID 38584157, 2024). "The gasdermin family has been shown to contain key executors of the cell pyroptosis process, and a proteolytic fragmentation of GSDMD has been found to be a main mediator of pyroptosis of RTECs during sepsis-induced AKI." (PMID 38515158, 2024). "This study reveals, for the first time, that cognitive impairment induced by sepsis involves the activation of GSDMD, increased levels of Drp1, mitochondrial injury, resulting in synaptic damage, and disrupted neural oscillations in the hippocampus." (PMID 38627764, 2024). "Previous research has found that GPX4 expression and lipid peroxidation were involved in GSDMD-mediated pyroptosis in sepsis." (PMID 38891111, 2024). "We then stained F4/80, CK7, CD3, and VEad in lung tissues following CLP with cleaved GSDMD to further investigate pyroptosis in immune cells in sepsis-induced lung damage." (PMID 38169584, 2024). "Studies have found that NLRP3/caspase‐1/GSDMD‐mediated pyroptosis plays an important role in the occurrence and development of sepsis, and inhibiting NLRP3 inflammasome‐mediated pyroptosis can reduce acute lung injury in sepsis." (PMID 39484787, 2024). "The hippocampus, vital for spatial memory, plays a pivotal role in understanding how Casp11 and GSDMD contribute to cognitive dysfunction in sepsis." (PMID 39179968, 2024). "Currently, inhibitors of pyroptosis including disulfiram 15 and necrosulfonamide 47 have been demonstrated to alleviate inflammatory cell death and sepsis by binding to GSDMD directly to disrupt cell pyroptosis." (PMID 38993566, 2024). "We then stained F4/80, CK7, CD3, and VEad together with cleaved GSDMD or TUNEL in lung tissues of CLP-treated mice to further investigate pyroptosis in immune cells in sepsis-induced lung damage." (PMID 38169584, 2024).
Sepsis (continued). "In sepsis, the activation of GSDMD facilitates the externalization of phosphatidylserine, thereby augmenting the procoagulant activity of TF on the surface of the cell membrane." (PMID 39445002, 2024). "Another clinical study from Southeast University investigates the effect and mechanism of lncRNA NBR2 regulating endothelial pyroptosis by targeting GSDMD in sepsis (ClinicalTrials.gov Identifier: NCT04427371)." (PMID 38543885, 2024). "For example, mice genetically lacking ACSS2 exhibited decreased cleavage of GSDMD in RTECs during the induction of sepsis, suggesting that GSDMD is a downstream effector of ACSS2 in the process of cell pyroptotic death during sepsis-induced AKI." (PMID 38515158, 2024). "Collectively, these investigations underscore that GSDMD indeed plays a crucial role in sepsis pathology." (PMID 38584157, 2024). "It comprises NLRP3, which detects danger and recruits molecules; caspase-1, essential for cytokine maturation and processing gasdermin D for cytokine release and sepsis; and ASC, bridging NLRP3 and caspase-1." (PMID 38922058, 2024). "Platelet pyroptosis exacerbates NET formation which releases S100A8/A9 to promote Gasdermin D (GSDMD)-dependent pyroptosis in mice with CLP-induced sepsis." (PMID 39040114, 2024). "During sepsis, caspase-11/GSDMD pathway was activated to control the release of neutrophil extracellular traps by neutrophils, implying GSDMD as a therapeutic target against sepsis." (PMID 39253076, 2024). "Our previous study demonstrated that sepsis-triggered canonical NLRP3 inflammasome activation cleaved GSDMD in the hippocampus, inducing neuronal pyroptosis and neuroinflammation, causing hippocampus-dependent memory impairments." (PMID 38627764, 2024). "Recent research has shed light on how O-GlcNAc modification of GSDMD can influence pyroptosis in the in the pathogenesis and progression of sepsis." (PMID 39742284, 2024). "The interaction between GSDMD and the complement system offers potential therapeutic targets for the treatment of sepsis." (PMID 39445002, 2024). "GSDMD has been recognized as the primary substrate for Caspases in pyroptosis, particularly in sepsis, while GSDME mediates pyroptosis in other diseases." (PMID 37962578, 2024). "In summary, our study reveals that the REGγ-Bim-GSDMD/E pathway is a novel regulatory mechanism of pyroptosis in sepsis-related tissue injury." (PMID 39349939, 2024). "Necrosulfonamide (NSA) is a small molecule that improves GSDMD-mediated mortality in a mouse sepsis model by inhibiting the formation of p30-GSDMD pores." (PMID 36755018, 2023). "Previous studies have demonstrated that that the classical pathway of necroptosis, RIPK1/RIPK3 pathway, can collaborate with the key protein of pyroptosis, GSDMD, to amplify inflammatory signals and exacerbate tissue damage during sepsis." (PMID 38161332, 2023). "Pyroptosis plays a critical role in the pathogenesis of sepsis, and mice unable to undergo caspase-11 or gasdermin D-dependent pyroptosis are protected from LPS-induced lethality." (PMID 37798443, 2023). "Remarkably, GSDMD-mediated pyroptosis is driven by lipid peroxidation in cases of lethal polymicrobial sepsis." (PMID 37627547, 2023). "Neutrophil GSDMD-mediated NETs promote sepsis-related lung, heart, kidney, and liver injury, whereas inhibiting GSDMD reverses the sepsis-induced damage in these organs 27, but the role of neutrophil GSDMD in SAE has not been identified." (PMID 37056920, 2023). "Collectively, CA prevents pro‐inflammatory cytokine secretion and pyroptotic cell death by directly blocking GSDMD activation and alleviates LPS‐induced sepsis in mice." (PMID 37090118, 2023). "Tea polyphenols nanoparticles scavenged reactive oxygen and nitrogen species via polyphenols-derived structure to inhibit oligomerization of GSDMD and cell pyroptosis in endotoxin-induced sepsis." (PMID 38022612, 2023).
Sepsis (continued). "As we have verified that SJS is able to modulate pyroptosis in sepsis animal model, next, we detected the protein level of GSDMD, and caspase-1 of MH-S cells treated with LPS and ATP along with different concentrations of SJS." (PMID 37062835, 2023). "Neutrophil GSDMD was essential for NET release in sepsis and promoted subsequent development of SAE." (PMID 37056920, 2023). "Another mechanism of organ damage is through the release of neutrophil extracellular traps (NETs), in which caspase-11 and GSDMD have been shown to play a crucial role in both sepsis-induced and SARS-CoV-2-infected models, contributing to organ dysfunction." (PMID 38002346, 2023). "Inhibition or deletion of GSDMD has been shown to have a protective effect on a variety of animal models of inflammatory diseases, such as sepsis and viral infections." (PMID 37275856, 2023). "In animal experiments, pyroptosis inhibition or GSDMD knockout can effectively protect mice from fatal sepsis 35-37." (PMID 37781519, 2023). "SESN2 also reduces gasdermin D (GSDMD)-dependent pyroptosis of splenic DCs in the context of sepsis via inhibiting PERK-ATF4-CHOP signaling-triggered NLRP3/ASC pyroptosome formation and Caspase-1 activation." (PMID 36841824, 2023). "Among them, four classes are implicated in sepsis, including GSDMA, GSDMB, GSDMD and GSDME, with GSDMD being the most widely studied." (PMID 38022612, 2023). "Irisin can decrease the IL-1 β and Gasdermin D (GSDMD) levels by regulating the mitochondrial ubiquitin ligase (MITOL)/GSDMD pathway, improving the levels of LDH and creatine kinase-MB, and reducing inflammation and cardiomyocyte scorch caused by sepsis." (PMID 37629199, 2023). "Targeting both caspase-11 and GSDMD is considered a potential therapeutic avenue for the treatment of septic shock and sepsis." (PMID 37049646, 2023). "The caspase-1 inhibitor VX765 inhibited caspase-1, suppressed the expression of GSDMD and its cleavage form GSDMD-NT, reduced the pyroptosis and sepsis-induced impairment of the blood–brain barrier and structural damage in the brain." (PMID 37891821, 2023). "Studies have shown that deleting GSDMD can block pyroptosis and provide protection against sepsis, systemic blood coagulation, and multiorgan damage." (PMID 38020710, 2023). "Deletion of GSDMD has been shown to protect against sepsis and improve survival in mouse models of sepsis, indicating the critical role of GSDMD in sepsis." (PMID 37275856, 2023). "Based on these findings, the GSDMD system is considered a potential therapeutic target for treating sepsis and warrants further investigation." (PMID 38020710, 2023). "First, we confirmed the GSDMD expression in neutrophils of peripheral blood in CLP-induced sepsis model using Elacre-PD-L1flox mice." (PMID 37056920, 2023). "CA prevents pro‐inflammatory cytokine secretion and pyroptotic cell death by directly blocking gasdermin D activation, and can obviously improve the survival rate of the sepsis mice to 80%." (PMID 37090118, 2023). "Studies showed that depletion of GSDMD only on neutrophils worsened the severity of sepsis in mice, while systemic depletion of GSDMD alleviated the severity of sepsis, highlighting the crucial role of NETosis in sepsis." (PMID 38022612, 2023). "Platelets play an important role in the pathogenesis of sepsis, and the expression of GSDMD in platelets is significantly upregulated in septic patients." (PMID 38022612, 2023). "In LPS-induced sepsis, caspase-11/GSDMD pathway activation promoted the release of ferritin from macrophages and increased serum ferritin concentrations." (PMID 38022612, 2023). "IRF2 can directly drive GSDMD transcription by engaging the promoter of GSDMD to induce pyroptosis in sepsis." (PMID 38022612, 2023). "Mangiferin, a flavonoid widely distributed in several herbs, inhibited NLRP3/caspase-1/-11-mediated GSDMD activation in sepsis." (PMID 38022612, 2023).
Sepsis (continued). "A recent study revealed that sepsis-derived S100A8/A9 induces GSDMD-dependent platelet pyroptosis in severe sepsis by upregulating the TLR4/NLRP3 signaling pathway, which leads to the release of oxidized mtDNA and promotes NETs formation." (PMID 37275856, 2023). "Previous clinical studies have reported elevated levels of NLRP3, GSDMD, IL-1β, and IL-18 in patients with sepsis." (PMID 38161332, 2023). "Two described key GSDMD roles during disseminated intravascular coagulation after lethal endotoxin sepsis models, but they described two different mechanisms of GSDMD function." (PMID 35455985, 2022). "Based on the RFWK inhibitory motif, we designed an RFWK peptide inhibitor to target caspase-1/11 activity and found the inhibitor substantially suppresses GSDMD cleavage and IL-1β release, as well as LPS-induced sepsis in mice." (PMID 36322773, 2022). "In murine sepsis models, gene deletion or antagonism of GSDMD with disulfiram reduced NET release and improved organ function, leading to enhanced survival in septic mice." (PMID 36059483, 2022). "To sum up, we revealed XBJ reversed NETs formation by reducing GSDMD excessive expression induced by sepsis." (PMID 36467039, 2022). "Murine studies demonstrated that endotoxin uses both TLR4 and caspase-11/gasdermin D (GsdmD) pathways to induce the release of HMGB1 from hepatocytes—the major source of circulating HMGB1 in sepsis." (PMID 35160068, 2022). "Mechanistically, the activation of the caspase-11/GSDMD pathway controls NET release by neutrophils during sepsis." (PMID 35967871, 2022). "Taken together, circ-Katnal1 enhanced inflammatory pyroptosis in sepsis-induced liver injury through the miR-31-5p/GSDMD axis." (PMID 35979014, 2022). "This is in line with the findings of more pyroptosis in primary knockin BMDMs in response to stimuli and also consistent with previous reports that GSDMD-mediated pyroptosis is primarily responsible for LPS-induced sepsis." (PMID 36322773, 2022). "Since the immune response during sepsis is partly mediated by caspase-1 and -11 induced GSDMD-pyroptosis, we used the Casp1/11-/- mice to study gasdermin expression during sepsis." (PMID 34996441, 2022). "In the process of sepsis, GSDMD is required for the formation of NETs, a special form of neutrophil death that releases chromatin structures into the extracellular space." (PMID 36467039, 2022). "In summary, downregulating circ-Katnal1 attenuated proinflammatory cytokine production and inflammatory pyroptosis during CLP-induced sepsis via upregulating miR-31-5p and downregulating GSDMD." (PMID 35979014, 2022). "The canonical and non-canonical inflammasome activation leads to caspase-1 and caspase-4/5/11 activation respectively, with subsequent GSDMD processing as a key regulator mechanism of inflammation during sepsis." (PMID 34996441, 2022). "Another anti-pyroptotic drug currently in clinical application is lncRNA NBR2, which regulates endothelial pyroptosis by targeting GSDMD in sepsis." (PMID 35673561, 2022). "When sepsis does occur, Gasdermin D (GSDMD) is cleaved following caspase-1/caspase-11 activation, resulting in pores formation, water influx and cell swelling." (PMID 36467039, 2022). "A previous study found that GSDMD N-terminal-mediated pyroptosis is dependent on the PLCG1 gene in sepsis." (PMID 35741587, 2022). "GSDMD appears to be a promising target for the treatment of sepsis by connecting pyroptosis and NET." (PMID 36059483, 2022). "Syringaresinol (SYR) improved cardiac function and alleviated myocardial injury in sepsis-induced cardiac dysfunction mouse via the estrogen receptor (ER)/SIRT1/NLRP3/GSDMD pathway." (PMID 35509275, 2022). "During sepsis, the genetic deletion or pharmacological inhibition of GSDMD with disulfiram prevented the formation of NETs, protecting mice from organ damage development and increasing survival." (PMID 35799268, 2022).
Sepsis (continued). "The findings of this study provide insights into the role of GSDMD in regulating intestinal barrier function in sepsis and provide a potential therapeutic target for the treatment of sepsis." (PMID 36589684, 2022). "The late stage of NET release also requires GSDMD, being in charge of producing pores in cell membrane to allow DNA extrusion, which is relevant to the detrimental events in sepsis, such as systemic inflammatory process and organ failure." (PMID 36059483, 2022). "Several studies have found that GSDMD is an essential therapeutic target for reducing the inflammatory response and organ dysfunction in sepsis." (PMID 36589684, 2022). "Of note, the upregulation of NLRP3, cleaved caspase-1 and cleaved GSDMD that are related to caspase-1-dependent pyroptosis was found in pneumonia-induced sepsis." (PMID 35508474, 2022). "Specific gasdermin D inhibitors are in preclinical development, but disulfiram, a drug that has been FDA approved since 1951, was recently shown to inhibit gasdermin D in macrophages and to increase survival after experimental sepsis in mice." (PMID 35133984, 2022). "The immunofluorescent staining revealed that XBJ reduced sepsis-induced GSDMD and caspase-11 excessive expressions in neutrophils isolated from lung tissues." (PMID 36467039, 2022). "We performed LPS-induced sepsis model on GSDMD-NLSL;LysM-Cre mice and found that the knockin mice were more susceptible to sepsis." (PMID 36322773, 2022). "It has been found that pyroptosis participated in the pathogenesis of sepsis-induced myocardial injury which was associated with the XIST/miR-150-5p/c-Fos axis and ER/SIRT1/NLRP3/GSDMD pathway." (PMID 35509275, 2022). "The expression of key inflammasome proteins NLRP3 and caspase-1 and pyroptosis-related proteins GSDMD, IL-1β, and IL-18 was decreased, suggesting that inhibition of pyroptosis also alleviated lung injury in mice with sepsis." (PMID 35188436, 2022). "Gpx4 deficiency in myeloid cells was also shown to increase disease severity in a murine model of polymicrobial sepsis as a result of an enhanced lipid peroxidation–dependent caspase-11 activation and consequently gasdermin D–mediated pyroptosis." (PMID 36069923, 2022). "Collectively, we demonstrated XBJ protected against sepsis-induced lung injury by reversing GSDMD-related pathway to inhibit NETs formation." (PMID 36467039, 2022). "Recent studies have revealed the determinant role of Gasdermin D- (GSDMD-) mediated pyroptosis in the pathogenesis of sepsis." (PMID 34707775, 2021). "Although the experimental evidence clearly shows that fluconazole or amphotericin B pretreatment worsens sepsis outcome by eliminating intestinal fungi and promoting GSDMD cleavage, it is prudent to translate it to the clinics." (PMID 34707775, 2021). "GSDMD is essential for LPS-induced lethal sepsis, which verifies the central role of GSDMD-mediated pyroptosis in determining sepsis outcome." (PMID 34707775, 2021). "Paradoxically, here we discovered that although disruption of caspase-1/11 aggravated C. albicans infection as previously reported, disruption of GSDMD, an effector molecule downstream of caspase-1/11, protected against C. albicans-induced sepsis." (PMID 34795266, 2021). "Here we find a key role for macrophage GSDMD in C. albicans infection and established it as a potential host-directed therapeutic target for C. albicans-induced sepsis." (PMID 34795266, 2021). "Despite the complexity of the host response to C. albicans, we clearly established GSDMD as a host component that exacerbates inflammatory responses during C. albicans-induced sepsis and can thus be targeted to combat C. albicans invasion." (PMID 34795266, 2021). "Excessive activation of STING1 pathway is involved in pathogenesis of sepsis and is recently reported to drive lethal coagulation in sepsis through GSDMD-dependent mechanism." (PMID 33796108, 2021).